CD163 (CD163 molecule)
Diseases named in the same sentence as CD163 in open-access papers (continued):
Sharing a sentence is not in itself a finding about the gene and the disease.
skin cancer (5 papers, 2018 to 2020). "In lesions of various skin cancers, CD163+ macrophages are a main component of TILs that can produce various chemokines by stimulating cancer-specific stromal factors such as POSTN, IL-4, and RANKL." (PMID 29643991, 2018). "Notably, the main population of TAMs in skin cancer is CD163+ M2 macrophages, with sCD163 as the activation marker, suggesting that CD163 activated with PD1 antibody should release sCD163 in the tumor microenvironment." (PMID 32707850, 2020). "Notably, the main population of TAMs in skin cancer is CD163+ M2 macrophages, with soluble (s)CD163 as the activation marker." (PMID 31417907, 2019). "Indeed, CD163+ TAMs expresses arginase 1 in several skin cancers such as EMPD and SCC." (PMID 29410946, 2018). "Since the main population of TAMs in skin cancer is CD163+ M2 macrophages, TAM activation releases soluble (s)CD163, suggesting its utility as a prognostic marker for anti-PD1 antibody treatment." (PMID 32707850, 2020).
subarachnoid hemorrhage (5 papers, 2012 to 2024). A serious neurological disorder characterized by intracranial hemorrhage into the subarachnoid space. "In turn, the knockdown of endogenous TSG-6 by siRNA elevated the (CD86+) M1 vs. (CD163+) M2 ratio in cerebral microglia and aggravated neurological deficits 24 h after subarachnoid hemorrhage." (PMID 39329947, 2024). "After subarachnoid hemorrhage, the intrathecal CD163-haptoglobin–hemoglobin system was saturated, as shown by the presence of extracellular hemoglobin despite detectable haptoglobin." (PMID 22380637, 2012). "Expression of CD163 on resident microglia and infiltrating macrophages has been described under various pathological conditions in the CNS parenchyma, including HIV encephalitis, subarachnoid hemorrhage, and in active as well as rims of chronic active MS lesions." (PMID 37715818, 2023). "This suggests that hemoglobin detoxification from the subarachnoid space after subarachnoid hemorrhage is not carried out only by resident macrophages (ED2+) and their CD163 mediated haptoglobin-hemoglobin uptake, but also via phagocytosis by activated (ED1+) macrophages." (PMID 33328892, 2020).
synovitis (5 papers, 2005 to 2022). Inflammation of a synovial membrane. "Adjusting for BMI, CRP was associated with radiographic knee osteophyte score (p=0.002), while CRPM was associated with synovitis of the knee (p=0.017), synovitis of multiple joints (p=0.008), and macrophage marker CD163 in serum (p=0.009) and synovial fluid (p=0.03)." (PMID 34465395, 2021). "PsA synovitis is characterized by prominent vascularization and an increased number of neutrophils, mast cells and CD163+ macrophages." (PMID 33898490, 2021).
thrombosis (5 papers, 2018 to 2025). "In our study, we observed a positive association of Sema7A/CD163 in thrombosis with poor prognosis of AIS." (PMID 38373967, 2024). "However, analyzing the thrombo-pathological characteristics of patients with AIS who received RS vs. NRS showed significant differences in the expression of biomarkers associated with AIS and thrombosis, such as CD163, NET, and CRP, between the two patient groups." (PMID 41036279, 2025). "Patients with higher CD68/CD163 ratios had approximately 68% increased odds of developing thrombosis compared to those with lower ratios." (PMID 41239536, 2025). "After filtering the plasma proteomic data from UK Biobank (UKB) participants diagnosed with I63.0 (cerebral infarction due to thrombosis) or I63.4 (cerebral infarction due to embolism), we assessed the correlation between plasma CD163 and TGFB1 levels." (PMID 41329022, 2025). "In order to determine predictive factor of thrombosis, the levels of soluble CD163, free hemoglobin and NO products were retrospectively measured on serum frozen at wAIHA diagnosis in 7 patients with VTE and 22 patients without VTE." (PMID 30408135, 2018). "A CD68/CD163 ratio > 1.63 correlated with shorter thrombosis-free survival (41.4 vs. 68.2 months; p = 0.001; hazard ratio [HR] 2.45, 95% confidence interval [CI] 1.45–4.14) and secondary myelofibrosis progression-free survival (48.3 vs. 79.0 months; p = 0.001; HR 2.67, 95% CI 1.55–4.60)." (PMID 41239536, 2025).
allergies (4 papers, 2013 to 2022). "IL-13 is implicated in the alternative activation of macrophages resulting in a pro-reparative CD206+CD163+ macrophage subset that antagonizes IFN-γ inflammatory actions and is implicated in humoral immunity, allergies, and anti-parasitic responses." (PMID 36220814, 2022).
atopic dermatitis (4 papers, 2018 to 2025). "Atopic dermatitis increased the expression levels of CD163, SOCS1, MIP-2, COX-2, HDAC3, COX-2, and MCP1 but decreased the expression of iNOS in a CXCL13-dependent manner." (PMID 30459600, 2018). "Atopic dermatitis increased the expression of cluster of differentiation 163 (CD163), a marker of M2 macrophages, but decreased the expression of inducible nitric oxide synthase (iNOS), a marker of M1 macrophages." (PMID 30459600, 2018). "Atopic dermatitis, in an SOCS1-dependent manner, decreased the expression of iNOS while increasing the expression of CD163 in BALB/c mouse." (PMID 30459600, 2018).
bacteremia (4 papers, 2012 to 2020). "sCD163, the soluble form of CD163, has been evaluated as a serum marker for bacteremia, and its levels have been shown to be correlated with clinical outcomes." (PMID 22693573, 2012).
celiac disease (4 papers, 2012 to 2022). An autoimmune genetic disorder with an unknown pattern of inheritance that primarily affects the digestive tract. "Of antigen-presenting cells (APCs) expressing HLA-DQ molecules in the celiac disease (CD) lesion, CD11c+ dendritic cells (DCs) co-expressing the monocyte marker CD14 are increased, whereas other DC subsets (CD1c+ or CD103+) and CD163+CD11c− macrophages are all decreased." (PMID 22438948, 2012). "Also, the staining reactions were strong in dual-colour indirect immunofluorescence staining of CD3+CD8− IELs and in an immunohistochemical panel (CD4, CD8, CD19, CD163, and FOXP3) consisting of markers known to be relevant for the pathogenesis of coeliac disease." (PMID 31730447, 2019).
E. coli infection (4 papers, 2020 to 2025). "Using intracellular flow cytometry, we then measured a subset of phenotypic markers (Arginase 1, iNOS, MHCII, and CD163), which classically represent pro- and antiinflammatory function following LOX-1 inhibition at 18–36 hours of E. coli infection." (PMID 36264633, 2022). "E. coli infection is attributed to IL10 secretion and CD163 up-regulation in PBMΦ-0 and PBMΦ-IL10." (PMID 31953452, 2020).
emphysema (4 papers, 2014 to 2024). "Furthermore, we detected the upregulation of cd163 (marker of mature tissue macrophages) and cd14 (involved in development of Th1 response), as found in CS-induced emphysema." (PMID 35241086, 2022).
esophageal squamous cell carcinoma (4 papers, 2017 to 2023). Esophageal squamous cell carcinoma (ESCC) is a type of esophageal carcinoma (EC) that can affect any part of the esophagus, but is usually located in the upper or middle third. "Low-dose of metformin also increased tumor-suppressive (CD11c+) and a decreased tumor-promoting (CD163+) macrophages in the patients with esophageal squamous cell carcinoma (ESCC)." (PMID 36614197, 2023).
follicular lymphoma (4 papers, 2020 to 2024). Follicular lymphoma is a form of non-Hodgkin lymphoma characterized by a proliferation of B cells whose nodular structure of follicular architecture is preserved. "Follicular lymphoma and CTRL tissue samples were immune stained for CD68, CD163 and tryptase to evaluate total macrophages, M2 macrophages, and mast cells, respectively." (PMID 35268349, 2022).
gout (4 papers, 2013 to 2023). A condition characterized by painful swelling of the joints, which is caused by deposition of urate crystals. "In contrast, CD14+ cells in gout patients showed marked expression of CD163, a marker for alternative activation of macrophages (M2)." (PMID 29056937, 2017). "In addition, anti-inflammatory features, including CD163 expression and IL-10 production from CD14+ cells, were inhibited in RA patients more prominently compared to those with gout." (PMID 32351318, 2020). "In addition, anti-inflammatory features, including CD163 expression and IL-10 production from CD14+ cells, were significantly higher in patients with gout than in those with RA." (PMID 29056937, 2017).
hemolysis (4 papers, 2013 to 2025). Disruption of the integrity of the erythrocyte membrane causing release of hemoglobin. "The macrophage scavenger receptor CD163 internalizes and degrades hemoglobin-haptoglobin (Hb-Hp) complexes built due to intravascular hemolysis." (PMID 35163309, 2022). "During conditions of excessive intravascular hemolysis Hp can be depleted from the blood, and in this cases free Hb may also be taken up by CD163 due to a weak affinity for CD163." (PMID 26111002, 2015). "The proinfammatory vasculotoxic effects of intravascular hemolysis are modulated by plasma hemoglobin and heme clearance via the haptoglobin/CD163 system and the hemopexin/CD91 system, respectively, and detoxification through the heme oxygenase/ferritin system." (PMID 25506596, 2013).
Hepatic steatosis (4 papers, 2017 to 2023). Steatosis is a term used to denote lipid accumulation within hepatocytes. "Our results showed a positive relation between the degree of hepatic steatosis and the expression profile of IL-4, IL-47, and CD163." (PMID 33906302, 2021). "We also detected a positive relation between the degree of hepatic steatosis and CD163 expression." (PMID 33906302, 2021).
Histiocytosis (4 papers, 2023 to 2026). An excessive number of histiocytes (tissue macrophages). "Erdheim-Chester disease (ECD) is a rare histiocytic disorder characterized by the infiltration of tissues with foamy, xanthomatous CD68/CD163-positive, CD1a-negative histiocytosis." (PMID 41994452, 2026).
injury (4 papers, 2015 to 2024). Damage inflicted on the body as the direct or indirect result of an external force, with or without disruption of structural continuity. "The soluble form of CD163 (sCD163) has been shown to increase in plasma after liver injury." (PMID 25645333, 2015). "In this study, the expression of CD163 was increased in the RvE1 group compared to that in the LPS group, which indicates that RvE1 might play an important role in the resolution phase of LPS-induced heart injury." (PMID 32256344, 2020).
intracerebral hemorrhage (4 papers, 2017 to 2024). A cerebrovascular disorder characterized by bleeding into one or both cerebral hemispheres including the basal ganglia and the cerebral cortex. "Although several studies have shown upregulation of CD163 after intracerebral haemorrhage, CD163 binding sites are limiting after SAH since free Hp-Hb complexes persist in the cerebrospinal fluid, possibly compounded by soluble CD163 shedding." (PMID 29104730, 2017). "Thus, CD163 was proposed as a target for treatment of intracerebral hemorrhage." (PMID 39451197, 2024).
ischemia (4 papers, 2013 to 2021). A hypoperfusion of the BLOOD through an organ or tissue caused by a PATHOLOGIC CONSTRICTION or obstruction of its BLOOD VESSELS, or an absence of BLOOD CIRCULATION. "Another group further investigated the dynamics of BAMs after cerebral ischemia in rodents and humans, revealing a significant fivefold increase of CD163+ BAMs with inflammatory phenotype in the perivascular and meningeal spaces at 3 days post-ischemia." (PMID 34881289, 2021). "Different inflammatory signals will either upregulate (anti-inflammatory) or downregulate (pro-inflammatory) CD163 expression, in which CD163+ cells proliferate in the injured brain 3–4 days following ischemia." (PMID 34944064, 2021). "We examined the CD163+ cells and the CD45+CD11b+ myeloid cells in the control brain tissue and the brain tissue at 16 h and 24 h post-ischemia." (PMID 30092836, 2018). "Depleting the CD163+ macrophage population had more effects in cortical rather than in subcortical regions after ischemia." (PMID 30092836, 2018). "Furthermore, CD163+ BAMs are involved in recruiting granulocytes, promoting vascular endothelial growth factor (VEGF) expression, and inducing vascular leakage during the 24 h post-ischemia." (PMID 34881289, 2021).
juvenile xanthogranuloma (4 papers, 2017 to 2025). A benign histiocytic tumor that occurs during childhood; it is distinct from Langerhans cell histiocytosis. "Both BCH and juvenile xanthogranuloma share similar immunohistologic markers: CD68, CD163, and Factor XIIIa." (PMID 40678378, 2025). "A few surface markers, including CD163, fascin, and factor XIII, are helpful to distinguish mixed histiocytic lesions (e.g., Erdheim-Chester or juvenile xanthogranuloma)." (PMID 35379272, 2022). "Juvenile xanthogranuloma (JXG) is a rare non-Langerhans cell (LCH) histiocytic disorder with histologic features characteristic of dermal dendrocytes (fascin+, CD1a−, CD207−) and macrophages (CD14+, CD68+, CD163+, and factor XIIIa+)." (PMID 28512266, 2017).
lung squamous cell carcinoma (4 papers, 2021 to 2024). "In addition, higher expression of CD163, CD206 (MRC1), and CD11b (ITGAM) in patients with lung squamous cell carcinoma was associated with lower overall survival." (PMID 38521953, 2024).
mastitis (4 papers, 2020 to 2025). Inflammation of breast tissue during lactation or postpartum due to an obstructed duct or infection. "The bta-miR-16a cluster contributes to the defense against mastitis by targeting the CD163 gene and regulating the expression of both anti-inflammatory and pro-inflammatory cytokines in dairy cattle." (PMID 40005551, 2025). "The studies indicate that miR-15a constitutes potential miRNA-mRNA regulatory pairs with target gene (IRAK2) for use as biomarkers to predict a mastitis response or indirectly affects the expression of CD163 gene in E. coli-infected mastitis cows." (PMID 35396568, 2022).
mesothelioma (4 papers, 2014 to 2023). A usually malignant and aggressive neoplasm of the mesothelium which is often associated with exposure to asbestos. "In our study, a similar outcome is found regarding M1/M2 ratio based on CD163/68 ratio and the prediction of survival in patients with mesothelioma." (PMID 25192022, 2014). "We found that the structural changes in M2 included ARG1, CD206, CD163, FN1, and MRP8, confirming the potential value of these markers to identify M2-like TAMs in patients with mesothelioma." (PMID 37958292, 2023). "We report that the expression of ChemR23 coding gene, CMKLR1, in breast and mesothelioma tumors positively correlates to the expression of TAM markers such as CD14, CD163, MRC1 and HLA-DRA, in agreement with ChemR23 detection restricted to macrophages in tumors from patients." (PMID 37539056, 2023). "The percentage of M2 macrophages of the total macrophage count was comparable between the surgery and non-surgery group and therefore, the CD163/CD68 ratio does not discriminate in favor of surgery in mesothelioma patients." (PMID 25192022, 2014).
myositis (4 papers, 2008 to 2023). "HRS-mediated induction of myositis results in a dramatic shift from M2-like macrophages expressing CD209f/C209g/CD163/Lyve1 marker genes (cluster 19) to macrophages expressing genes associated with alternative phenotypes (clusters 1, 2, and 6)." (PMID 37809058, 2023). "Infiltration of macrophages into myositis tissues and the presence of CD163 positive (M1) macrophages are described in myositis muscle." (PMID 23758833, 2013).
pancreatic neuroendocrine tumor (4 papers, 2021 to 2025). Pancreatic endocrine tumor, also known as pancreatic neuroendocrine tumor (PNET), describes a group of endocrine tumors originating in the pancreas that are usually indolent and benign, but may have the potential to be malignant. "In pancreatic neuroendocrine tumors high CD163 positivity in macrophages showed a significant association with metastatic status." (PMID 39462379, 2024). "Additionally, the infiltration of CD68+ macrophages or CD163+ M2-polarized macrophages was associated with the high risk of recurrence as an independent disease-specific survival prognosis factor for postoperative patients with pancreatic NETs." (PMID 35740577, 2022). "However, the clinical significance of CD47 expression and CD163+ TAMs in pancreatic neuroendocrine tumor (PanNET) remains unclear." (PMID 33765961, 2021). "Although CD163+ macrophages tend to increase in density and have an altered plump/epithelioid morphology after neoadjuvant peptide receptor radionuclide therapy, they are not related to progression-free survival in pancreatic NETs." (PMID 35740577, 2022).
thymoma (4 papers, 2014 to 2024). A neoplasm arising from the epithelial cells of the thymus. "The percentage of CD163+ TAMs varied from 4.38% to 23.98% with a median of 9.23% in thymoma samples, and 6.53% to 33.26% with a median of 14.55% in thymic carcinoma samples." (PMID 25499804, 2014). "Regarding the positivity for CD163, the thymoma and thymic carcinoma samples were categorized into two groups on the basis of the 7.28% cut-off point that indicates the median in normal thymic samples." (PMID 25499804, 2014). "We examined the difference in the distribution profiles between TAMs and DCs in thymic epithelial tumors, and found a higher percentage of CD163+ TAMs and a lower percentage of S100+ DCs in thymic carcinoma tissues than in thymoma tissues." (PMID 25499804, 2014). "A high percentage of CD163+ TAMs was observed in 93.8% (15/16) of thymic carcinoma samples and 64.2% (34/53) of thymoma samples (including 2 type A, 12 type AB, 6 type B1, 10 type B2 and 4 type B3), which were statisfically significantly different (p = 0.024)." (PMID 25499804, 2014). "Thymic carcinoma hosts an increased proportion of CD163+ compared to thymomas." (PMID 36551568, 2022). "Previous studies have found that there is a higher proportion of CD163+ in TC than in thymoma." (PMID 34033229, 2021). "Although the percentage of CD68+ TAMs was not significantly different between thymoma and thymic carcinoma, in thymic carcinoma, which is associated with more frequent invasive growth and distant metastases, a higher percentage of CD163+ TAMs was found." (PMID 25499804, 2014). "Moreover, the percentage of samples with a large number of CD163+ TAMs was higher in the thymic carcinoma samples than in the thymoma samples." (PMID 25499804, 2014). "However, the percentage of sample with a large number of CD163+ TAMs was significantly higher in thymic carcinoma than in thymoma (15/16 versus 34/53, p = 0.024)." (PMID 25499804, 2014).
ulcerative colitis (4 papers, 2013 to 2025). An inflammatory bowel disease involving the mucosal surface of the large intestine and rectum. "The identification of TLR2, IFNG, and CD163 as hub genes suggests their potential utility as predictive biomarkers for ulcerative colitis diagnosis and disease monitoring." (PMID 41300749, 2025). "Anti-TNF-α antibody treatments, such as infliximab or adalimumab, have been found to attenuate aberrant macrophage activation by significantly reducing CD163 expression on circulating CD14+ monocytes, and normalised circulating sCD163 levels, in patients with ulcerative colitis." (PMID 33923959, 2021).
acral melanoma (3 papers, 2019 to 2025). "We then immunohistologically examined the expression of stromal periostin and the infiltration of CD163+ M2 macrophages in human acral lentiginous melanomas (n = 94) and analyzed the statistical associations with clinicopathological variables." (PMID 30621220, 2019). "Additionally, a recent study has identified a specific molecular subtype of invasive acral melanoma (the “proliferation” phenotype, C3) characterized by high immune cell infiltration, including immunosuppressive APOE+/CD163+ macrophages." (PMID 40362334, 2025).